IL6 (interleukin 6)
Diseases named in the same sentence as IL6 in open-access papers (continued):
Sharing a sentence is not in itself a finding about the gene and the disease.
ovarian carcinoma (continued). "In ovarian cancer, CAFs promote tumor invasion and growth through the secretion of a number of chemokines, cytokines, and growth factors like CCL5, IL-6, IL-8, HB-EGF, and TGF-α, among others." (PMID 30380628, 2018). "Plasma levels of Il-6 and TPO were significantly higher in ovarian cancer patients with thrombocytosis." (PMID 30441823, 2018). "Our study demonstrates that in ovarian cancer, TNFR2 expression can be selectively decreased on all T cells, and predominantly on Tregs, by blockade of bioactive IL-6 within ascites." (PMID 29163543, 2017). "The observation that PNA3 treatment also decreased IL-6 levels indicates that PNA3-targeting enhanced the response of ovarian cancer initiating cells to CDDP." (PMID 28420874, 2017). "The activation of CXCR4 results in the upregulation of the prometastatic cytokines IL-6, CXCL12, and TNFα in ovarian cancer cells and increases metastasis." (PMID 28275576, 2017). "They secrete IL-6, IL-8/CXCL8, CCL2, and adiponectin, which act on cancer cells via their respective receptors to support ovarian cancer cell metastasis." (PMID 28275576, 2017). "Although IL-6, VEGF, and CA 125 all were elevated in ovarian cancer patients, and bFGF and M-CSF were decreased in these patients, only IL-6 and VEGF were significantly elevated in stagees I and II cancer patients." (PMID 28487810, 2017). "In pancreatic cancer, CAF-induced IL6 secretion promotes cancer cell migration and CAF-secreted CCL18 has been shown to promote tumour invasion in breast and ovarian cancer." (PMID 28987144, 2017). "Autocrine production of IL6 and IL8 confers cisplatin and paclitaxel resistance in ovarian cancer cells, due to increased expression of both multidrug resistance-related genes and apoptosis inhibitory proteins." (PMID 26820579, 2016). "Molecular factors not included in our array, such as gp100, ERCC, CD44, CD147, c-met, IL-6, ALDH, CD117 and BMP2 have also been studied in the context of chemoresistance in ovarian cancer." (PMID 27258020, 2016). "Early studies have also reported enrichment of pro-inflammatory cytokines such as IL-6, CXCL10, and CD54 in ascites and have a pro-metastatic role in ovarian cancer progression." (PMID 27825119, 2016). "In a variation on this theme, but also involving AhR, a positive feedback loop encompassing IL-6 expression and STAT3 has recently been described in various tumor cells, including ovarian cancer." (PMID 26343197, 2015). "In ovarian cancer, increased levels of EGF stimulate IL6 secretion, which promote the mobility and resistance to chemotherapy via the JAK/STAT3, SHP-2/Ras, MAPK, and PI3K/Akt signaling pathways." (PMID 26356073, 2015). "In light of various publications highlighting the importance of IL-6/IL-6R signaling in ovarian tumor biology and the results described here, we are supportive of clinical trials to study whether antagonizing IL-6R is a viable treatment strategy for ovarian cancer." (PMID 25658637, 2015). "Ko and colleagues demonstrated that ovarian cancer cells induce normal omental fibroblasts to express CAF markers and mitogenic factors such as IL-6 and chemokine (C-X-C motif) ligand 12 (CXCL12) that stimulated tumor cell proliferation." (PMID 24567915, 2014). "Omental fibroblasts that are stimulated by ovarian cancer cells have been found to secrete levels of VEGF-A and IL-6 that are, respectively, 5- and 10-fold higher than the levels secreted by unstimulated fibroblasts." (PMID 24567915, 2014). "Thus IL-6 produced from tumor cells may be a pathophysiologic trigger of tumor-induced thrombocytosis across different cancer types in a manner similar to that proposed for ovarian cancer." (PMID 23864954, 2013). "In human ovarian cancer cells, IL8 is up-regulated together with IL6 by the nuclear factor-kappa B (NFκB) pathway." (PMID 23675535, 2013). "Antibodies against IL6 and inhibitors of proteins involved in its pathway, such as JAK2 and STAT3, are currently in development for use in ovarian cancer." (PMID 22481926, 2012).
ovarian carcinoma (continued). "IL-6 also activated HIF-1α, which clearly indicates that HIF-1α perhaps is regulated through STAT3 in ovarian cancer cells." (PMID 22280969, 2012). "In ovarian cancer cell lines, LPA contributes to angiogenesis by stimulating the neovascularizing factors IL-6, IL-8, and vascular endothelial growth factor (VEGF) expression, and ATX modulates cell responsiveness to VEGF." (PMID 21799791, 2011). "Thus, interference with IL-6 pathway may offer opportunities for ovarian cancer therapy." (PMID 21619709, 2011). "In 21 out of 30 ovarian carcinoma patients, PCF IL-6 levels were found to exceed those seen in PCFs of patients with gastrointestinal cancer." (PMID 10682675, 2000). "The ability to form NETs in ovarian cancer may be stimulated by NE, VEGF, G-CSF and cytokines: TNFα, IL-2, IL-6, IL-17A in serum." (PMID 40391215, 2025). "Furthermore, the EGFR/ERK/NFκB and EGFR/PI3K/NFκB pathways play crucial roles in cancer cell proliferation and invasion, which in turn increase IL6 and IL6R expression in chemo-resistant ovarian cancer cells." (PMID 40427188, 2025). "The average VEGF-A and IL-6 levels were lower in EMS and BeCy, compared to ovarian cancer." (PMID 40076450, 2025). "Targeting IL-6 to modulate macrophage polarization and reduce hepcidin production may offer a therapeutic strategy to manage CRA in patients with advanced ovarian cancer." (PMID 40330466, 2025). "IL-6 may facilitate ovarian cancer progression through additional pathways, such as IL-6/JAK2/STAT3, IL-6/STAT3/HIF-1α, and mtDNA/toll-like receptor (TLR9)/NF-κB/IL-6." (PMID 39061859, 2024). "Currently, the application of IL-6/IL-6Rα/gp130 blockers as anticancer agents has not been extensively studied, especially for ovarian cancer." (PMID 38998933, 2024). "The levels of serum IL‐6, TNF‐α, and IFN‐γ are helpful to the clinical diagnosis of ovarian cancer recurrence, and the specificity of serum TNF‐α in predicting recurrence in ovarian cancer patients and the area under the ROC curve are higher than IL‐6 and IFN‐γ." (PMID 37904699, 2023). "In this study, we evaluated a panel of 8 biomarkers, including B7-H3, IL-6, PLA2G7, Tie-2, GDF-15, IL-6 R alpha, sSDC1, and VCAM-1 selected based on their reported relevancy to ovarian cancer and multiplexing feasibility as a customized magnetic bead-based 8-plex immunoassay." (PMID 37357306, 2023). "Ovarian cancer cells secrete IL6 and IL6Rα (soluble form sIL-6R) through trans-signaling sIL6R-IL6 in the pro-inflammatory microenvironment cells that do not express transmembrane receptor to facilitate angiogenesis via increasing the VEGF expressions." (PMID 37792745, 2023). "In our study, in the comparison between early (I and II according to the FIGO classification) and late stages of ovarian cancer (III and IV according to the FIGO classification), there was a statistically significant impact of the algorithm HE4, Ca125, CRP, PCT and Il-6." (PMID 37373969, 2023). "IL-6 was found to activate the JAK/STAT3 pathway and could promote tumor metastasis in ovarian cancer by enhancing the proliferation, migration, and invasion of tumor cells." (PMID 38038814, 2023). "The sources of IL-6 are from both malignant and normal cells, with PBMC from ovarian cancer patients reported to secrete higher concentrations of IL-6 compared to healthy controls, and IL-6 is also expressed at different concentrations within ovarian cancers of various grades and stages." (PMID 36765633, 2023). "The expression of some immune-related molecules, such as IL-4, IL-6, IL-10, and GM-CSF, were analyzed, but none of them was found to be related to the induction of B7-H4 expression in ovarian cancer cells." (PMID 36609273, 2023). "The LGALS3 inhibitor GB0139 has shown promise in acute lung injury where its mechanism of action involves reducing IL-6, TNF-α, and MIP-1α69, and thus may also prove efficacious in ovarian cancer where TNF-α plays a role in EMT initiation and maintenance." (PMID 38086828, 2023).
ovarian carcinoma (continued). "In this study, the serum IL‐6 level in recurrence ovarian cancer patients was significantly higher than that in nonrecurrence ovarian cancer patients." (PMID 37904699, 2023). "Since IL-6, IL-8, PD-L1, IDO and ROS have been shown to inhibit the killing function of NK cells, we treated NK-92 cells with the supernatant of MUC16- treated neutrophils and evaluated the ability of NK-92 to kill ovarian cancer cell line OVCAR-3." (PMID 37644468, 2023). "Currently, the application of IL-6/IL-6Rα/gp130 blockers as anti-cancer agents has not been extensively studied, much less for ovarian cancer." (PMID 37047012, 2023). "In ovarian cancers specifically, CAFs can induce angiogenesis through the secretion of IL-6, COX-2, and CXCL1, while ovarian cancer cells are reported to induce CAFs to secrete CXCL12, IL-6, and VEGF-A expression via HOXA9, leading to angiogenesis." (PMID 36672620, 2023). "A natural product, apigenin, reduced AXL expression in ovarian cancer cell lines without affecting IL6 production and STAT3 phosphorylation, suggesting the selectivity of the STAT proteins in the regulation of AXL expression." (PMID 36835239, 2023). "Thrombocytosis is a paraneoplastic syndrome of ovarian cancer, and the mechanism is mainly explained by the higher plasma levels of thrombopoietin and IL-6 in patients with thrombocytosis compared to those without thrombocytosis." (PMID 36681847, 2023). "Many drugs were found to inhibit IL-6 signaling, including siltuximab and sirukumab, although, none of them currently show promising outcomes in ovarian cancer treatment." (PMID 37047012, 2023). "The serum IL‐6, TNF‐α, and IFN‐γ levels were closely related to the recurrence of ovarian cancer." (PMID 37904699, 2023). "Interleukin-6, a functional counterpart of Upd3 in mammals, is also induced; accordingly, the activation of the JAK-STAT pathway is observed in several tumors, such as breast and ovarian cancer." (PMID 37626857, 2023). "We have previously reported that ONA inhibits tumor progression in sarcoma and ovarian cancers by regulating macrophage activation; however, this is the first evidence that ONA can inhibit STAT 3 activation induced by IL-6, which was derived from macrophages in SCLC cells." (PMID 36961655, 2023). "There was no influence of procalcitonin on the sensitivity of Il-6 in the diagnosis of ovarian cancer." (PMID 37373969, 2023). "Furthermore, exogenously added IL-6 was shown in a separate study to activate the JAK2/STAT3 pathway and promote migration in SKOV3 and OVCA433 ovarian cancer cell lines." (PMID 35565396, 2022). "The hierarchical clustering revealed a group of proteins that have previously been reported to be expressed at elevated levels in ovarian cancer serum samples, including: CA125 (MUC16), HE4, MSLN, MK, KLK8, KLK11, NECT4, FOLR1, as well as KLK13, KLK14, and IL6." (PMID 35804849, 2022). "These included, among others, VEGF—known to promote ovarian cancer neovascularization, TGF-β1—recognized as a mediator of EMT and increased ovarian cancer cell invasion, proinflammatory and ovarian cancer cell growth-promoting IL-6, and pro-migratory HGF." (PMID 35883110, 2022). "In epithelial ovarian cancer, the elevated expression of STAT4 in epithelial cells induced MSCs derived from adipose and bone marrow to obtain CAF-like features, which in turn promoted EMT and peritoneal metastasis of ovarian cancer by secreting CXCL12, IL-6 and VEGF-A." (PMID 36185262, 2022). "EVs released from the ovarian cancer spheroids in response to cisplatin elevated the levels of MMP that digests extracellular matrices, augmented migration of MSCs and increased secretion of IL-6, IL-8 and VEGF-A." (PMID 33946403, 2021). "Thus, the anti-IL-6 antibody siltuximab has been shown to reduce STAT3 activation and angiogenesis in IL-6-producing xenografts of intraperitoneal ovarian cancer and reduces VEGF levels in patients with ovarian cancer." (PMID 34206393, 2021).
ovarian carcinoma (continued). "Herein, we investigate a high-performance microfluidic detection platform to conduct a novel panel of multiple biomarkers for the early detection of ovarian carcinoma, which include CA125, HE4, OPN, MSLN, Hsp70, CA153, AFP, IL-6, and IL-8 using a microfluidic chip." (PMID 35423342, 2021). "Although BOTs are not entirely recognized as malignant tumors and are not seen as a necessary process of transformation into ovarian cancer, in this study, we found some biomarkers related to EMTs, such as IL6, AKT1, MAPK3, SRC, TWIST1, and TGFB1." (PMID 33921111, 2021). "Moreover, it has been demonstrated that estrogen, IL-6 and CXCL8 are capable of interacting with each other to regulate the growth of epithelial ovarian cancer through cascade amplification effect via an ERα pathway." (PMID 34717710, 2021). "In ovarian cancer cell lines HO8910 and SKOV3, it was demonstrated that TAMs or cytokines released from them, like IFN-γ, TNFα, IL-10, and IL-6, are responsible for the upregulation of PD-L1 expression in the surface of these cells, but no modification in its mRNA was observed." (PMID 33540543, 2021). "The aim of this study was to investigate whether IL-6, IL-8, and TNF-α have sufficiently high sensitivity and specificity to be considered as new useful markers for diagnosis of ovarian cancer." (PMID 34573967, 2021). "The identification of CYCS, VEGFA, IL6, UQCRC1, UQCRFS1, COX5B, ACKR3/CXCR7, and FYN as pro-tumorigenic nodes designates them as the novel and potentially druggable targets for effective targeted adjuvant therapy for ovarian cancer." (PMID 34439877, 2021). "In addition, the level of IL-6 determined in ascites was correlated with the serum level of the CA125, and 92% of patients with malignant ovarian tumors had CA125 > 35 UI/mL and IL-6 > 45 pg/mL." (PMID 34572929, 2021). "We hypothesized At-EE inhibited the expression of IL-6 and VEGF from ovarian cancer cells through mediating NF-kB or STAT3." (PMID 32190078, 2020). "Moreover, IL-6 and IL-10 released by blood monocytes-derived TAMs activate the pro-survival STAT3 signaling in ovarian cancer cell lines and cancer cells isolated from patients’ ascites, keeping them alive." (PMID 32456078, 2020). "The PF IL-6 levels differed between the different FIGO stages or Kurman-Shih types of ovarian cancer; however, the difference was not statistically significant (p > 0.05)." (PMID 33062717, 2020). "And p-STAT3/NF-kB/IL-6 and VEGF is a cascade amplification loop in ovarian cancer." (PMID 32190078, 2020). "Moreover, the serum levels of Cyr61, IL-6 and CRP in advanced stage of ovarian cancer were much higher than those in early stage." (PMID 31766991, 2019). "Moreover, a wide variety of inflammatory agents, including interleukin-6 (IL-6), Akt, lysophosphatidyl acid (LPA) and protein kinase C (PKC) have been found to be elevated in ovarian cancer." (PMID 31202269, 2019). "In addition to Cyr61 and IL-6, CRP serum level in advanced ovarian cancer was significantly higher than those in the early stage." (PMID 31766991, 2019). "Knockdown of p110α expression alone or in combination with IL-6/STAT3 inhibition did not reduce ovarian cancer cell resistance to carboplatin induced by ascites medium." (PMID 29930760, 2018). "The aim of our present study was to evaluate the implication of the p110α PI3K subunit in ovarian cancer chemoresistance acquisition, and to evaluate whether the JAK/STAT pathway could mediate resistance to PI3K inhibitors through secretion of IL-6." (PMID 29930760, 2018). "PTX could induce NF-κB and cJUN activation to promote IL-6, IL-8, VEGF and MCP-1 productions via a TLR4/MyD88-dependent pathway and resisted drug-induced apoptosis in ovarian cancer." (PMID 29486738, 2018). "Moreover, several soluble factors of mesothelial origin have been found to stimulate other vital elements of ovarian cancer cell progression, including proliferation (CXCL8/IL-8, IL-6), migration (CXCL12/SDF-1, HA), and invasion (LPA)." (PMID 28956065, 2018).
ovarian carcinoma (continued). "We aimed to evaluate the implication of the p110 alpha PI3K subunit in ovarian cancer chemoresistance acquisition, and to evaluate whether the STAT3 pathway can mediate resistance to PI3K inhibitors through secretion of IL6." (PMID 29930760, 2018). "The concomitant increased production of CXCL12, IL6, and VEGFA by CAFs within the tumor microenvironment could enable peritoneal metastasis of ovarian cancer via induction of the EMT program." (PMID 30380628, 2018). "Additionally, adipocytes of the omentum contribute to a protumor TME by secreting IL-6, IL-8, CCL2, and adiponectin, which support ovarian-cancer cell metastasis." (PMID 30200478, 2018). "In addition, hospicells synergized with ovarian cancer cells to secrete increased amounts of proangiogenic VEGF, IL-6, and CXCL8/IL-8." (PMID 28956065, 2018). "IL-6/STAT3 and PIK3CA inhibition did not reverse platinum chemoresistance in ovarian cancer and IL-6 levels cannot be considered as a marker of sensitivity to platinum-based chemotherapy." (PMID 29930760, 2018). "Our results showed that down-regulation of S1PR1 or S1PR3, but not S1PR2, effectively inhibited S1P-induced VEGF, IL-8 and IL-6 secretion in ovarian cancer cells." (PMID 29088837, 2017). "In addition to the well-known ovarian cancer serum biomarkers CA125 and HE4, we identified six additional proteins, MK, hK11, KLK6, FRα, PRSS8, and IL-6, that had previously been reported as serum biomarkers for ovarian cancer." (PMID 29051715, 2017). "Many of the same proteins that were identified by unsupervised hierarchical clustering and by linear regression analysis, were also significantly higher in the late stage ovarian cancer patients relative to the healthy women, e.g. MK, KLK6, hk11, CXCL13, FR-alpha, IL-6, and FADD." (PMID 29051715, 2017). "Proteins encoded by NFκB target genes include anti-apoptotic, growth-promoting, proinvasive, proangiogenic and immunesuppressive proteins, exemplified by BCLX-L, IL-6, IL-8, VEGF, and PD-1L, which explains its multifaceted role in ovarian cancer progression and therapy resistance." (PMID 28275576, 2017). "Herein we report that human ovarian cancer patient derived ascites comprises pro-inflammatory tumor microenvironment (TME), of which elevated levels of IL-6 increased EOC cell invasion through JAK2-STAT3 signaling in parallel with increased expression of EMT related genes." (PMID 27825119, 2016). "Targeting IL-6, IL-6R or JAK2/STAT3 may offer an efficient management of ascites induced migration and invasion in ovarian cancer patients." (PMID 27825119, 2016). "Here we screened 36 pro-inflammatory cytokines and found IL-6 expression only in ovarian cancer patient derived ascites but absent in peritoneal fluids from benign condition." (PMID 27825119, 2016). "Similar to ovarian cancer, miR-192 treatment mediated a robust downregulation of EGR1 and HOXB9 levels and significant decreases in several angiogenic factors including IL6, IL8 and EFNA1; consistent with the pattern observed after siEGR1/siHOXB9 treatment." (PMID 27041221, 2016). "Minocycline inhibited IL-6 in monocytes, in central nervous system parenchyma and/or infiltrating cells, and in ovarian cancer cells, but not in vitro in retinal microglia." (PMID 27019421, 2016). "Interleukin 6 (IL6) is a proinflammatory cytokine that induces EMT in cervical and ovarian cancers." (PMID 26356073, 2015). "As IL-6 is central to the autocrine signaling loop that contributes to IDO expression, inhibition of IL-6 may have therapeutic benefit in ovarian cancer." (PMID 26343197, 2015). "The addition of exogenous sIL-6R did not further promote the invasion of ovarian cancer cells induced by IL-6, suggesting that IL-6Rs (IL-6R and sIL-6R) produced from cancer cells are enough to activate IL-6/IL-6R signaling." (PMID 25658637, 2015).